SPOP (speckle type BTB/POZ protein)
Diseases named in the same sentence as SPOP in open-access papers (continued):
Sharing a sentence is not in itself a finding about the gene and the disease.
cancer (continued). "Taken together, our data raise the possibility that disruption of the SPOP-BRAF regulatory axis may promote malignant transformation of cancer cells." (PMID 36585710, 2022). "Moreover, mutations in the SPOP-BRAF-binding interface disrupt the SPOP-BRAF regulatory pattern and promote aberrant MAPK/ERK activation and malignant transformation in cancer cells." (PMID 36585710, 2022). "Our data raise the possibility that disruption of the SPOP-BRAF regulatory axis may promote the malignant transformation of cancer cells." (PMID 36585710, 2022). "Interestingly PRAD has relatively few frequently mutated driver genes, with SPOP being the only gene mutated in over 10% of samples, yet PRAD tends to acquire more putative methylation driver events than any other cancer." (PMID 34871444, 2021). "We conducted this meta-analysis to confirm whether SPOP was an effective biomarker to predict clinical stage, cancer differentiation and survival." (PMID 34838022, 2021). "Interestingly, SPOP mutants in different types of cancer yield opposing effects on BET protein degradation by differential ubiquitination and sensitivity to BET-BD inhibitors." (PMID 34540900, 2021). "Similarly, funnel plot showed no publication bias for the meta-analysis of the correction between the expression of SPOP and cancer stage, tissue differential and overall survival." (PMID 34838022, 2021). "Based on these results, we posited that differential levels of androgen receptor (AR) signaling in SPOP-mutant vs. ERG-fused cancers might be at the root of the incompatibility between the driver events." (PMID 33531470, 2021). "As SPOP may play a dual role in cancer, it has been suggested that it exerts its biological function in a cancer type-specific manner." (PMID 34680332, 2021). "However, gene expression signatures of PCa with SPOP mutations and TMPRSS2:ERG fusions appeared to be similar, leading to the inference that increased ERG activity was a main oncogenic driver in cancers with SPOP mutations." (PMID 34066106, 2021). "Our results also showed that SPOP was highly expressed in most ccRCC clinical tissues and ccRCC cell lines, and the knockdown of SPOP in A498 cells suppressed ccRCC tumorigenesis and progression by reducing cancer cell growth, migration, and invasion." (PMID 34021128, 2021). "SPOP is an important molecule that is paid a large amount of attention by researchers in recent years, which plays critical roles during normal development and cancer progress." (PMID 34838022, 2021). "SPOP expression level was insignificant between cancer and adjacent tissue in total." (PMID 34838022, 2021). "Importantly, APC/CCdh1 tends to promote cancer cells to adapt to immune response by destabilizing SPOP, as cullin 3-SPOP is the direct E3 ligase to target PD-L1 for degradation." (PMID 35006464, 2021). "Thus, SPOP not only can predict cancer prognosis, but also is a novel therapeutic target to affect anti-cancer therapy effectiveness." (PMID 34838022, 2021). "Moreover, the gene expression signatures shared between SPOP mutation and TMPRSS2-ERG fusion cancers consisted largely of genes expressed in normal prostate tissue." (PMID 34066106, 2021). "Moreover, cancer-associated mutations in the MATH domain disrupt the formation of the SPOP condensate by preventing the interaction between substrates and SPOP." (PMID 34334791, 2021). "At the molecular level, the incompatible cancer pathways are driven by opposing functions in SPOP." (PMID 33531470, 2021). "Dysregulation of SPOP has also been reported in other cancers." (PMID 33023230, 2020). "Systematic approaches are needed to screen the substrates of SPOP in human cancer." (PMID 31901237, 2020). "This study uncovered the first mechanism of SPOP regulation in any type of cancer." (PMID 33158056, 2020).
cancer (continued). "For example, downregulation of miR-145 and miR-543 could increase the SPOP level, and inhibit the migration and invasion of cancer cells." (PMID 31901237, 2020). "SPOP mutations observed in human cancers are clustered in the MATH domain, suggesting that they may promote cancer via altering the stability of its substrates." (PMID 32512734, 2020). "Thus, more studies should be carried out to clarify the function of SPOP in these two cancers and identify several potential substrates of SPOP during the carcinogenesis of CC and OC." (PMID 31901237, 2020). "Since evidence has indicated oncogenic or suppressive roles of the SPOP protein depending on the specific cancer types, the SPOP protein could function as a novel therapeutic target for treating human cancers." (PMID 31901237, 2020). "Several miRNAs have also been identified to be involved in the regulation of SPOP in human cancers." (PMID 31901237, 2020). "We will also note that SPOP is a promising therapeutic target for cancer treatments." (PMID 31901237, 2020). "Moreover, we highlight the critical role of SPOP in tumorigenesis based on three major categories: physiological evidence (animal models), pathological evidence (human cancer specimens) and biochemical evidence (downstream ubiquitin substrates)." (PMID 31901237, 2020). "In fact, CRCs harboring mutant RAS/RAF or SPOP can be more effectively killed by drug combinations through catastrophic ISR associated with features of immunogenic cell death, which is believed to help achieve more durable cancer control in patients." (PMID 33135632, 2020). "In this review article, we describe the structure and regulation of SPOP in human cancer." (PMID 31901237, 2020). "The dysregulated expression and validated substrates of SPOP in cancers." (PMID 31577764, 2019). "Interestingly, by further stratified analyses according to cancer type, our findings indicated that SPOP overexpression exhibited a close correlation with LNM in ccRCC." (PMID 31577764, 2019). "To investigate whether our findings are generalizable to other SPOP mutant organoids, we examined the anti‐cancer effect of JQ1 and CPI‐637 co‐treatment or NEO2734 alone using multiple PCa organoid lines." (PMID 31559706, 2019). "Subgroup analysis of pooled HRs for OS in cancer patients with high SPOP expression." (PMID 31577764, 2019). "Decreased SPOP expression could predict poor prognosis of cancer patients, suggesting that SPOP protein may be a useful prognostic biomarker in cancer patients." (PMID 31577764, 2019). "Considering that several limitations existed, it should be cautious to appreciate the conclusion, and well-designed, large-scale studies are imperative to verify the biological and prognostic significance of SPOP in cancers, especially in a single type of cancer." (PMID 31577764, 2019). "Second, the inconsistent cut-off values of SPOP expression might impact on the precision of the prognostic role of SPOP in human cancer." (PMID 31577764, 2019). "Our results showed that low SPOP expression was correlated with worse survival in patients with various carcinomas, indicating that SPOP may act as a potential prognostic marker." (PMID 31577764, 2019). "Of these primary cancers, 75% were classified into seven subtypes, defined by either specific gene fusions of ETS transcription family members (ERG, ETV1, ETV4, and FLI1) or mutations (SPOP, FOXA1, and IDH1)." (PMID 29581876, 2018). "FOXA1-mutant cancers share similar molecular features with SPOP-mutant cancers." (PMID 29581876, 2018). "Notably, cancer-derived SPOP mutants disrupted their binding with HDAC6 and thereby failed to promote HDAC6 degradation." (PMID 28599312, 2017).
cancer (continued). "Furthermore, depletion of SPOP using several independent shRNAs elevated the endogenous HDAC6 protein abundance in multiple cancer cell lines including HCT116, DU145, PC3, and HeLa." (PMID 28599312, 2017). "Thus, SPOP elicits context-dependent functions in cancer development, which is influenced in part by its different subcellular distributions." (PMID 27200299, 2016). "In this cancer type, wild-type SPOP, but not cancer-associated SPOP mutants, targets estrogen receptor-α for ubiquitination and degradation." (PMID 27200299, 2016). "A plausible explanation is that the SPOP mutants from different cancers might show differential effect on the regulation of certain substrates." (PMID 25766326, 2015). "Or SPOP acts to inhibit Gli2-mediated transcriptional activation and thereby block the effect of Gli2 on the activation of target genes, thus further impact on initiation of cancer cell proliferation, migration, invasion and apoptosis." (PMID 25204354, 2014). "The other known drivers of the PCa early development (in fusion-negative cancers) are also several: SPOP mutation, SPINK overexpression, CHD1 deletion and TAK1 loss, as well as chromosomal losses not characterized in terms of genes involved." (PMID 25277175, 2014). "Notably, cancer-derived SPOP mutants disrupt this interaction, preventing HDAC6 degradation." (PMID 40521202, 2025). "Moreover, mutations in SPOP, frequently found in PCa, may compromise the function of the DDIT3-SPOP axis, contributing to therapy resistance and more aggressive cancer phenotypes." (PMID 40521202, 2025). "However, the definitive role of SPOP in these cancers requires further investigation." (PMID 40521202, 2025). "However, in the context of tumorigenesis, disruptions in SPOP's phase-separating ability can lead to the stabilization of oncogenic proteins that should otherwise be degraded, promoting uncontrolled cell proliferation and cancer progression." (PMID 40521202, 2025). "The SPOP-Gli2 axis, therefore, plays a critical role in maintaining the balance between cell survival and death, and its dysregulation could offer potential therapeutic targets for cancer treatment." (PMID 40521202, 2025). "Therefore, a mechanism whereby SPOP-mediated RIPK3 regulation may sensitize cancer cells to death through SPOP modulation was proposed." (PMID 39540935, 2024). "Although this study did not establish in vivo relevance for this pathway, future research involving combined treatment with SPOP inhibitors and necroptosis-inducing stimuli or anti-cancer drugs might enhance anti-cancer efficacy in chemoresistant cancer cells in in vivo models." (PMID 39540935, 2024). "Moreover, there are still several reports recovered the significant role of SPOP in cancers." (PMID 39074086, 2024). "Thus, while the contributions of SPOP to cancer establishment or progression are likely through deregulation of a manifold of its substrates, our work suggests that IRF1 may be one of them." (PMID 37622993, 2023). "Speckle type BTB/POZ protein (SPOP) may have cancer promoting or inhibiting effects." (PMID 37941785, 2023). "Cancer-associated SPOP mutations impair Geminin K27-linked poly-ubiquitylation and lead to replication stress and cell death upon ATR kinase inhibition, implying that cancers with defective SPOP-Geminin signaling might be responsive to ATR inhibitors treatment." (PMID 35136173, 2022). "Among 6 up-regulated cancer driver genes, 4 genes encode proteins known to function as negative regulators of cell proliferation (CDKN2A); inducers of apoptosis (BAX); tumor suppressor (RPL22); inhibitors of transactivation of insulin promoter by recruiting a repressor complex (SPOP)." (PMID 36879662, 2022). "Thus, a meta-analysis to investigate the impact of SPOP on cancers was warranted." (PMID 34838022, 2021).
cancer (continued). "And based on our research results, down-regulated SPOP expression could predict clinicopathological characters and poor prognosis, suggesting that SPOP protein had the potential to function as prognostic biomarker in cancer patients." (PMID 34838022, 2021). "Therefore, the potential mechanisms of SPOP in cancers were not fully understood." (PMID 34838022, 2021). "However, further stratified analyses according to cancer type demonstrated the relationship between SPOP overexpression and LNM was positive in ccRCC (OR = 5.26; 95% CI: 1.66–16.68, P = .005, fixed-effect model) but negative in non-ccRCC (OR = 0.36; 95% CI: 0.21–0.62, P < .001, fixed-effect model)." (PMID 31577764, 2019). "However, the predictive value of SPOP remains controversial in human cancers." (PMID 31577764, 2019). "Together, our data identify the tumor suppressor SPOP as an upstream negative regulator for HDAC6 stability, and SPOP loss-of-function mutations might lead to elevated levels of the HDAC6 oncoprotein to facilitate tumorigenesis and metastasis in various human cancers." (PMID 28599312, 2017). "However, it warrants further in-depth studies to explore whether cancer cells with SPOP-mutant genetic status are more sensitive to HDAC6 specific inhibitors due to elevated HDAC6 protein abundance." (PMID 28599312, 2017). "In PCa, evidence suggests that SPOP mediates ITCH ubiquitination and degradation, thereby protecting against cancer metastasis." (PMID 40521202, 2025). "Importantly, by targeting the downstream effects of SPOP loss—particularly the accumulation of ZBTB3 and its upregulation of SHH—these therapies could address the unique oncogenic mechanisms in SPOP-mutant cancers, potentially improving patient outcomes with reduced off-target effects." (PMID 40521202, 2025). "In conclusion, SPOP's role in ubiquitinating and destabilizing Twist1 is crucial for controlling EMT levels and mitigating aggressive cancer behaviors." (PMID 40521202, 2025). "We further assessed the protein levels of SPOP, RIPK1, and RIPK3 in representative cell lines of 5 cancer types." (PMID 41122967, 2025). "In cancer cells, cyclin D–CDK4/6-dependent phosphorylation of speckle-type POZ protein (SPOP)/Cullin-3 ubiquitin ligase complex destabilizes PD-L1 via proteasome-mediated degradation, but inhibition of CDK4/6 significantly elevates PD-L1 level." (PMID 39103548, 2024). "Small molecule disrupting the interaction between SPOP and PTEN is able to inhibit cancer cell proliferation." (PMID 38409107, 2024). "Similarly, the cancer-associated BRAF-T121I mutant did not co-localize with SPOP." (PMID 36585710, 2022). "De-ubiquitinase DUB3 binds to BRD4, but not BRD2/3, via a specific C-terminal motif (CTM), antagonizes SPOP-mediated BRD4 ubiquitination, and promotes BRD4 de-ubiquitination and stabilization, leading to BET-BD inhibitor resistance in cancer cells." (PMID 34540900, 2021). "Here, we show that SPOP- and ERG-mutant cancer subtypes are driven by antagonistic tumorigenic pathways involving fundamentally different roles of SPOP and androgen receptor signaling levels." (PMID 33531470, 2021). "Using Aurora A-as7 kinase, we have identified several direct targets, including PHLDA1, LIMK2, ALDH1A1, SPOP, YBX1, and TWIST1, in cancer cells." (PMID 34066036, 2021). "The nuclear speckle-type pox virus and zinc finger (POZ) protein (SPOP), a representative substrate-recognition subunit of the cullin-RING E3 ligase, has been characterized to play a dual role in tumorigenesis and cancer progression." (PMID 31901237, 2020). "LPD3 cancer samples had over-representation of ETS and PTEN gene alterations, and under-representation of CDH1 and SPOP gene alterations (P < 0.05, χ2 test)." (PMID 32203215, 2020). "Furthermore, we note that SPOP could be a promising therapeutic target for cancer treatment." (PMID 31901237, 2020).
cancer (continued). "SPOP directly interacts with CYCLIN E1, poly-ubiquitinates CYCLIN E1 in vivo and in vitro, and represses cancer-related phenotypes induced by CYCLIN E1 expression." (PMID 30237511, 2019). "Intriguingly, our pre-experiment found that SPOP was obviously inhibited in NSCLC tissues compared with that in adjacent normal lung tissues, suggesting that SPOP functions as a cancer suppressor gene (TSG)." (PMID 30607139, 2018). "Importantly, cancer-derived SPOP mutations disrupted the binding between SPOP and HDAC6 and failed to promote HDAC6 poly-ubiquitination and subsequently degradation, which might lead to elevated levels of HDAC6 to promote tumorigenesis." (PMID 28599312, 2017). "SPAST, SPOP and STX18 were found expressed in the epithelium of benign and cancer areas in both patient cohorts." (PMID 26863016, 2016). "The expression pattern of three corresponding antigens were established in benign and cancer tissue by immunohistochemistry and qPCR: SPAST (Spastin), STX18 (Syntaxin 18) and SPOP (speckle-type POZ protein)." (PMID 26863016, 2016). "In particular, we will focus on three Cul3 substrate adaptors, kelch-like ECH-associated protein (Keap1), kelch-like family member 20 (KLHL20), and speckle type BTB/POZ protein (SPOP), with the intent to highlight novel targets in cancer therapy." (PMID 27200299, 2016). "SPOP is localized in the nucleus of cells with droplet characteristics in membrane-less organelles, and when co-expressed with DAXX, it can form droplet-like SPOP/DAXX bodies via LLPS, which can reduce DAXX levels by ubiquitylating DAXX, effectively inducing apoptosis in cancer cells." (PMID 40642070, 2025). "Correlation analysis showed that SPOP and RIPK1 were positively correlated in all 5 cancer types." (PMID 41122967, 2025). "In the context of cancer, SPOP/RIPK1/RIPK3 axis is dysregulated across multiple cancer types, and the combination of the Smac mimetic SM164 enhances the antitumor efficacy of sunitinib in tumors with high expression of SPOP/RIPK1." (PMID 41122967, 2025). "The result indicated that most of cancer group (16/23) had a significantly lower SPOP level than normal group." (PMID 39074086, 2024). "SPOP interacts directly with SRC-3 and promotes ubiquitination and proteolysis in cancer cells." (PMID 38104650, 2024). "Additionally, the CNV condition and expression level of ASF1A, CDKN2A, MAGOHB, NADK, SPOP, and ARC were remarkably correlated in most cancer types." (PMID 37497116, 2023). "Given that BRAF is frequently hyperactivated in various human cancers, we explored whether BRAF is an authentic substrate of the CRL3-SPOP complex, and whether BRAF activity is dysregulated in SPOP-mutated cancers." (PMID 36585710, 2022). "SPOP, a CRL3 substrate adaptor protein, plays an important role in the development of some cancers." (PMID 36474188, 2022). "Hence, though SPOP was mainly expressed in adjacent normal tissue cells but less staining in RCC cancer cells,the role of SPOP expression in cancer development is context and substrates dependent." (PMID 36474188, 2022). "Moreover, cancer-associated BRAF mutations disrupted the BRAF-SPOP interaction and allowed BRAF to evade SPOP-mediated ubiquitination, thereby upregulating MAPK/ERK signaling and enhancing the neoplastic phenotypes of cancer cells." (PMID 36585710, 2022). "Egger’s test was conducted in the SPOP difference expression between cancer tissue and adjacent tissue, and the result indicated no publication bias (P = 0.98)." (PMID 34838022, 2021). "Cancer-derived SPOP mutants failed to promote PD-L1 degradation by poly-ubiquitination because of their deficiency in binding to PD-L1." (PMID 34830179, 2021). "Different expression and activation levels of GLI3-FL regulators (SPOP, androgen receptor, PP2A, CBP, SET7, MED12) or regulators of GLI3-R (PKA, GSK3β, βTrCP) in cancer cells in comparison to healthy cells might also promote cancer cell growth and survival." (PMID 32245491, 2020).